TNF (tumor necrosis factor)
Diseases named in the same sentence as TNF in open-access papers (continued):
Sharing a sentence is not in itself a finding about the gene and the disease.
Sepsis (continued). "Our data suggest that ketamine administration to macrophages stimulated by CA-MRSA is associated with blunting of the TNF response to these virulent pathogens, and suggest that these findings may have therapeutic significance in MRSA sepsis." (PMID 21266054, 2011). "It was found that many substances that act as mediators, which are elevated in sepsis and septic shock, such as tumor necrosis factor (TNF-α), interleukin (IL-1β), and a factor called complement anaphylatoxin (C5a), also have cardiodepressant properties in vitro." (PMID 22758615, 2011). "Herein, we did not further explore the well described anti-inflammatory effects of dexmedetomidine (beyond HMGB1 levels); however, dexmedetomidine reduces systemic levels of IL-6 and TNF-α following lipopolysaccharide infusion in rats and following cardiac surgery and sepsis in humans." (PMID 21702944, 2011). "Given the important role of TNF in sepsis, and the importance of staphylococcal sepsis in children, such suppression could have a therapeutic impact." (PMID 21266054, 2011). "Acid instillation increased TNF-α plasma concentrations as compared to sepsis (P = 0.005)." (PMID 22204611, 2011). "Moreover, PD-L1 blockade significantly improved survival, prevented sepsis-induced depletion of lymphocytes, increased tumor necrosis factor-alpha and IL-6 productions, decreased IL-10 production, and enhanced bacterial clearance in mice after CLP." (PMID 21418617, 2011). "However, serial responses of IL-1β, TNF-α and IL-6 from PBMCs still need to be elucidated in patients with severe sepsis." (PMID 21939530, 2011). "Sepsis results from a host inflammatory response to infection and is characterised by high circulating concentrations of inflammatory cytokines such as tumor necrosis factor (TNF)-α, interleukin (IL)-1β, IL-6 and IL-8." (PMID 20085628, 2010). "While CpG methylation can mediate more sustained suppression of certain genes, the promoters of several of the inflammatory genes suppressed in sepsis, including TNF-α, IL-6, IL-12 p40, and iNOS, contain few CpG motifs and are therefore less susceptible to this form of epigenetic regulation." (PMID 20585389, 2010). "The IL-10/TNFα ratio has been proposed as a prognosis indicator in sepsis and in leptospirosis." (PMID 20076757, 2010). "Measurement of TNF-α and IL-6 at the early phase of sepsis may be helpful to evaluate severity of disease and to estimate outcome." (PMID 22615611, 2010). "Standardized tests for the assessment of monocytic HLA-DR expression and ex vivo LPS-induced monocytic TNF-α release have recently been developed and these biomarkers may help to guide immunotherapy for sepsis." (PMID 20652004, 2010). "The concentrations of Ang-2 in this and other human sepsis studies are higher than those used in in-vitro studies, and may sensitize endothelial cells to lower concentrations of TNFα." (PMID 20482750, 2010). "Additionally, treatment with ghrelin in these sepsis models reduced serum concentrations of proinflammatory cytokines like TNF-α and IL-6." (PMID 20500817, 2010). "Interestingly, the British Society of Rheumatology recommended that previous sepsis on a TJA that remains in situ is a definitive contraindication of TNFα blocker use." (PMID 20637100, 2010). "Indeed, our results suggest PLD1 as a novel target for treating inflammatory diseases, where TNFα play key roles: these include diseases ranging from sepsis to respiratory and autoimmune diseases; all diseases with considerable unmet medical need." (PMID 20463923, 2010). "The relationship between TNFα/−308 SNP and sepsis has been studied extensively." (PMID 21274447, 2010). "On the other hand, TNF-α which is a pleiotropic predominantly macrophage-derived cytokine is thought to be involved in pathophysiological responses in cases of severe injury or sepsis." (PMID 20130823, 2009).
Sepsis (continued). "Well in line with this data, Orfanos and colleagues reported a strong relationship of Ang-2 with TNF-alpha in critically ill patients, suggesting that the latter may participate in the regulation of Ang-2 production in sepsis." (PMID 19416526, 2009). "Serum TNF-α concentration was elevated after 24 hours in the Sepsis-group (P < 0.05 vs. Sham)." (PMID 19594914, 2009). "Serial estimation of Interleukin-6 (IL-6) and Tumor Necrosis Factor-Alpha (TNF-α) and their correlation with mortality in sepsis in elderly patients and to determine the influence of gender on cytokine production and mortality in elderly patients with sepsis." (PMID 19881187, 2009). "TNF-α plasma levels correlate with the severity of sepsis and with patients' outcome." (PMID 19594900, 2009). "We thus established a human in vivo sepsis model (the human endotoxin model) in order to investigate the effect of glutamine on the response of TNF-α, IL-6, cortisol and white blood cell (WBC) subpopulations to a standardized inflammatory stimulus (intravenous injection of E. coli endotoxin)." (PMID 19173710, 2009). "Levels were higher in sepsis than in non-sepsis patients with a clear association to markers of the inflammatory response including white blood cell count, CRP, procalcitonin, and with the proinflammatory cytokines IL-6, IL-10, and TNF-α." (PMID 19545363, 2009). "In doing so, LPS-induced MKP-1 could prevent prolonged TNF-α production as in sepsis which may lead to severe damage to the host." (PMID 20017901, 2009). "TNF-α plasma level were already declined 48 and 96 hours after sepsis induction." (PMID 19594900, 2009). "However, it has been shown that complete elimination of TNF-α after CLP-induced sepsis coincides with increased mortality." (PMID 19196475, 2009). "Inflammatory status was assessed in sepsis patients by measuring TNF-α and IL-10, to elucidate whether it could account for differences observed in MMPs and TIMP-1." (PMID 19799791, 2009). "It is well tolerated and decreases TNF production in adults and preterm infants with sepsis." (PMID 19063731, 2008). "Previous studies have demonstrated that proinflammatory cytokines play a critical role in the initiation and progression of sepsis syndrome and that TNF-α, IL-1β, and IL-6 are important mediators of hemodynamic, metabolic, and immunologic alterations in the host during sepsis." (PMID 18680601, 2008). "Furthermore, successful HMGB1-targeted therapies in experimental sepsis, arthritis and brain ischaemia strongly down-regulate in vivo synthesis of TNF." (PMID 18346273, 2008). "Previous studies have demonstrated that proinflammatory cytokines play a critical role in the initiation and progression of sepsis syndrome and that TNF-α, interleukin (IL)-1β, and IL-6 are important mediators of hemodynamic, metabolic, and immunologic alterations in the host during sepsis." (PMID 18680601, 2008). "We compared cytokine concentrations among patients with severe sepsis and septic shock, and observed that concentrations of IL-1β, IL-6, IL-7, IL-8, IL-10, IL-13, IFN-α, MCP-1 and TNF-α were significantly increased in septic shock as compared with severe sepsis." (PMID 17448250, 2007). "Research to evaluate the production of cytokines like IL-1, IL-6 and TNF-α by activated microglia in septic patients might strengthen the hypothesis of the role of microglia in sepsis and co-existing neurological symptoms." (PMID 17224051, 2007). "In our study, the serum TNF-α and IL-1β levels were significantlyincreased in newborns with sepsis." (PMID 18274637, 2007). "This included traditionally evaluated cytokines (IL-1β, IL-6, IL-8, IL-10 and TNF-α) and a number of cytokines that are not commonly associated with sepsis (IL-7, IL-13, IFN-γ and MCP-1)." (PMID 17448250, 2007). "Data indicate that SNPs of TNF-α, Il-1β, PAI-1, and CD14 may be associated with a poor prognosis from sepsis." (PMID 17877801, 2007).
Sepsis (continued). "Genetic variations within the TNF and IL-10 genes may influence mortality rates in patients with sepsis." (PMID 16859504, 2006). "• Dopexamine infusion significantly reduced release of TNF-α, which is an early marker of sepsis." (PMID 16893450, 2006). "Our group, as well as others, has shown that TNF-α levels are increased in the context of sepsis." (PMID 16503969, 2006). "We recently reported that the TNF-α-308A allele did not affect the risk for sepsis but increased mortality in septic infants." (PMID 16611358, 2006). "To extend and validate this study in vivo, we decided to use the anticancer drug daunorubicin, as TNF-α, one of the main cytokines involved in sepsis, may induce devastating effects after in vivo injection." (PMID 12966434, 2003). "Furthermore, exosomal Rmrp levels in patients with sepsis were negatively correlated with HLA‐DR expression of monocytes or AMs and TNF‐α or lactate production after LPS stimulation in vitro, whereas they were positively correlated with patients’ sequential organ failure assessment (SOFA) scores." (PMID 41178622, 2026). "Specificity of SAE-related biomarkers: while biomarkers like cytokines (e.g., IL-6, TNF-α), S100B protein, and other markers of neuronal injury are elevated in both sepsis and SAE, their levels may be particularly associated with brain dysfunction in sepsis." (PMID 40529149, 2025). "Moreover, a low dose of DEX could increase glucocorticoid receptor-α levels and decrease plasma levels of TNF-α and IL-1β in the kidney, alleviating sepsis-induced kidney injury." (PMID 40872555, 2025). "Mechanistically, LPS-stimulated monocytes from immunosuppressed sepsis patients show significantly attenuated TNF-α secretion than controls, making monocytic TNF-α production below 200 ng/L under LPS stimulation serving as a diagnostic threshold for immunosuppression in sepsis patients." (PMID 40364841, 2025). "Animals were randomized into four groups: control, vitamin E, sepsis, and sepsis plus vitamin E. Serum oxidative stress markers, thiol-disulfide parameters, and inflammatory mediators, including C-reactive protein, interleukin-40, and tumor necrosis factor-alpha, were measured." (PMID 41196905, 2025). "Estrogen is known to exert protective effects against sepsis by modulating immune responses, acting primarily as an anti-inflammatory agent that dampens the expression of proinflammatory cytokines such as IL-6 and TNF-α, which are typically elevated during septic episodes." (PMID 41318782, 2025). "In the context of sepsis, a significant elevation in oxidative stress arises primarily from the excessive generation of reactive oxygen species (ROS), a process largely mediated by proinflammatory cytokines such as interleukin-6 (IL-6), interleukin-1 (IL-1), and tumor necrosis factor-alpha (TNF-α)." (PMID 41268545, 2025). "IFN-γ and TNF can act synergistically to induce inflammatory cell death in a variety of cell types, contributing to disease pathology in inflammatory bowel disease, sepsis and SARS-CoV-2 infection, as well as promote apoptosis of pancreatic β cells in Type 1 diabetes." (PMID 40148285, 2025). "Likewise, anti–Tumor Necrosis Factor-alpha (anti–TNF-α) and anti–Interleukin-1 (anti–IL-1) therapies, which neutralize key cytokines in the early storm, showed limited efficacy and potential harm in broad sepsis populations." (PMID 41009426, 2025). "From these proteins, TNFα, IL-1α, Lck, NOS2, SOD2 and CD36 were selected for validation by Western blot on murine bone marrow-derived macrophages due to their relevant roles in the NF-κB, iNOS, oxidative stress, and phagosome signaling pathways, which are closely associated with sepsis pathogenesis." (PMID 40725160, 2025). "Notably, Siv@NMs treatment achieved significantly greater reductions in MPO-DNA, H3cit, TNFα, and IL-6 levels, further validating the enhanced therapeutic efficacy of the nanoparticle formulation in suppressing systemic NETosis and inflammation during sepsis." (PMID 40574078, 2025).
Sepsis (continued). "On the 3rd to 7th day of sepsis progression, the immune system enters a paralysis phase, characterized by a marked reduction in the expression of pro-inflammatory factors in M1 macrophages, as evidenced by decreased secretion of TNF-α, IL-1β, and other cytokines." (PMID 41488672, 2025). "Furthermore, in a clinical trial, anti-TNF-α increased the mortality rate of patients with sepsis." (PMID 40699834, 2025). "Similarly, during infection and sepsis, insulin resistance is promoted in hepatocytes via interleukin (IL)-1beta, tumor necrosis factor and IL-6 and gluconeogenesis in the liver via a systemic neuroendocrine response, including the release of cortisol, norepinephrine and epinephrine." (PMID 40843859, 2025). "Lastly, we found that injecting LPS in Il18−/−, Ifng−/− and Il1b−/− mice treated with TNF-neutralizing antibodies abrogated the cellular effects validated above in all cases but lung granulocytes, suggesting that other pathways are likely at play for specific processes triggered by sepsis." (PMID 38191855, 2024). "Although RIC has been shown to lower levels of IL-6, TNF-α, and IL-1β and improve survival in animal models of sepsis, whether this concept inspired by animal studies has an impact on inflammatory cytokines stimulated by COVID-19 has not been previously explored." (PMID 36445625, 2024). "It has been observed that sepsis-induced endothelial cell activation escalates systemic inflammatory markers such as IL-1β, IL-6, and TNF-α, as well as the production of reactive oxygen species, factors that may accelerate the onset of sepsis-associated delirium (SAD)." (PMID 38357643, 2024). "Since severe sepsis is accompanied by systemic inflammation that results from excessive release of cytokines into the systemic circulation, it has been observed that the serum levels of TNF-α and IL-6 were markedly enhanced 6 h after multiple injections of 5 μg Ec-OMVs in mice." (PMID 39201409, 2024). "In addition, OXY could counteract the sepsis-induced flow in the pro-inflammatory cytokine TNF-α and block the shift of macrophages from a neutral to a pro-inflammatory state." (PMID 39845795, 2024). "Along with these changes, the mRNA levels of inflammatory mediators such as tumor necrosis factor-α (Tnf-α), chemokine ligand 2 (Ccl2), interleukin-6 (Il-6), interleukin-1β (Il-1β), and nitric oxide synthase 2 (Nos2) also demonstrated a marked elevation in the sepsis group." (PMID 38705396, 2024). "Thus, we predicted that the mechanisms of TNF-induced dysfunction could also be observed in human sepsis." (PMID 39543125, 2024). "Moreover, network pharmacology indicated that oxidative stress and inflammation are associated with sepsis-induced ALI; therefore, we detected the expression of oxidative stress factors (MPO, ROS, MDA, and SOD) and inflammatory factors (TNF-α, IL-6, and IL-1β) in LPS-stimulated HUVECs." (PMID 38445620, 2024). "Although previous literature indicate that the pro-inflammatory response may be impaired in preterm newborns, serum levels of monocyte-derived cytokines, such as TNF-α and IL-6, vary highly between newborns and can reach adult-like concentrations during sepsis." (PMID 38562936, 2024). "Additionally, our investigation revealed that intervention with BBR could diminished the activation of NF-κB signaling in myocardial cells and decreased the expression levels of TNF-α and IL-1β in myocardial tissues of sepsis rats." (PMID 39568588, 2024). "Thus, we evaluated the cytokine production ability of BM monocytes from naïve and from LPS-treated mice and found that BM monocytes from LPS-treated mice showed significantly lower production of TNF-α, a representative cytokine involved in sepsis induction, and CXCL1." (PMID 39040105, 2024). "Moreover, it has been demonstrated that the administration of anti-TNF antibodies could prevent shock, organ dysfunction and death in a baboon Escherichia coli model of sepsis." (PMID 38521954, 2024).
Sepsis (continued). "While the clinical use of NK cell-based therapies for the treatment of infection and/or sepsis are still in development, our findings suggest TNF signaling is a highly valuable pathway and specific targeting of TNFR1 or TNFR2 could be exploited in the future of NK cell-based immunotherapies." (PMID 39543125, 2024). "Regarding TNF-alpha, the most accurate predictor for neurological complications in the early neonatal period, as identified by our study, one meta-analysis highlighted a moderate diagnostic accuracy of TNF-α in identifying both early-onset and late-onset neonatal complications and sepsis." (PMID 38804370, 2024). "Sepsis (sepsis) is a systemic inflammatory response triggered by infection, and its pathologic features include overproduction of peripheral inflammatory factors (e.g., IL-1β, IL-6, TNF-α), which ultimately leads to cytokine storm and multiple organ dysfunction syndrome (MODS)." (PMID 39720715, 2024). "Thus, this study indicates that metformin, by regulating the AMPK/SIRT1/PGC-1α pathway, could reduce reactive oxygen species and inflammatory cytokines (IL-1β, IL-6, IL-8, and TNF-α) in a mouse model of sepsis." (PMID 38791227, 2024). "According to previous research, narcolepsy patients tend to secrete higher levels of cytokines, including IL-2, tumor necrosis factor, IL-4, and IL-13, which could be the reason for narcolepsy being a protective factor against severe sepsis and 28-day mortality in sepsis patients." (PMID 38343642, 2024). "The pathogenesis of septic shock, an extreme manifestation of sepsis characterized by a profound drop in blood pressure, involves an inflammatory stimulus triggering the production of pro-inflammatory mediators such as tumor necrosis factor (TNF) and interleukin (IL)-1." (PMID 38690455, 2024). "The TNF signaling pathway has a critical role in modulating immune cell responses as it can elicit a multitude of effects, including fever, apoptosis, cachexia, inflammation, suppressed tumor growth and viral replication, and sepsis responses through induction of IL1 and IL6." (PMID 39051372, 2024). "It plays an important role in sepsis as an anti-inflammatory, improves endothelial dysfunction, and promotes gluconeogenesis, and its main mechanisms of action include down-regulation of pro-cytokines, such as TNF-α, inhibition of innate immune system activation and maintenance of vasodilatory tone." (PMID 39178201, 2024). "It has been suggested that elevated TNF-α could be a non-causal associate of sepsis and that insufficient TNF-α blockade may account for the failure of anti-TNF-α treatment." (PMID 39134731, 2024). "Similarly, the serum TNF‐α and IL‐6 levels were significantly higher in the model group than those in the vehicle group, while the MAF pretreatments (10 and 20 mg/kg) markedly reduced the increased serum TNF‐α and IL‐6 levels in the sepsis mice, and the differences were significant (p < .05)." (PMID 38455195, 2023). "However, it has been shown that TNF-α, IL-6, IL-1 and IFN-γ are elevated in sepsis, cancer and other catabolic states, and may jointly cause muscle atrophy by increasing the expression of NF-κB." (PMID 38017491, 2023). "Therefore, blocking TNF-α-induced necroptosis might be a useful approach to mitigating massive cytokine release, preventing severe sepsis and, consequently, improving clinical outcomes." (PMID 36765040, 2023). "The Mg‐Tob motor conveyed satisfactory anti‐inflammation protection by neutralizing multiple pro‐inflammatory cytokines involving TNF‐α, IL‐6 and IL‐1β both in vitro and in vivo, which ensured it as an excellent candidate to prevent the development of highly heterogeneous inflammation in sepsis." (PMID 37818787, 2023). "Bacteremia coinfections with malaria could enhance the clinical severity of anemia and sepsis by decreasing cyclooxygenase (COX)-2 and prostaglandin E2 (PGE2) expression, and these mediators were associated with TNF-α, IFN-γ, and IL-10 production in coinfected individuals." (PMID 36716305, 2023).